TNF (tumor necrosis factor)
Diseases named in the same sentence as TNF in open-access papers (continued):
Sharing a sentence is not in itself a finding about the gene and the disease.
dermatitis (continued). "Initiation of skin inflammation by P. acnes involves activation of inflammatory cells, monocytes, keratinocytes and sebocytes and subsequent secretion of inflammatory cytokines and chemokines such as IL-1α, IL-1β, IL-6, IL-8 and TNF-α 43-45." (PMID 35414779, 2022). "Our findings suggest a hypothesis that topical ROCEN can potentially reduce pro-inflammatory cytokines such as TNF-α and IL-8, resulting in lipid homeostasis of the skin barrier in the lesion site and improvement of dermatitis symptoms." (PMID 34488737, 2021). "TNF-α is produced by keratinocytes and plays an important role skin inflammation." (PMID 34202301, 2021). "In conclusion, we could demonstrate that dermatitis and tumor development in ΔKerOTULIN mice depends on the cytotoxic activity of TNF driving FADD- and RIPK1 kinase-dependent death of keratinocytes." (PMID 34625556, 2021). "TNF-α and IL-6 are prominent cytokines in the pathogenesis of skin disorders." (PMID 33525403, 2021). "The role of TNF-α and nitric oxide in skin inflammation has been well documented previously." (PMID 32512874, 2020). "Regarding inflammatory cytokines, imiquimod-induced skin inflammation was reported to be ameliorated but not abolished in IL-17 receptor A-deficient mice and that the inflammation was mediated by TNF-α and IL-6, suggesting their importance in the inflammation." (PMID 32456211, 2020). "Considering our results, amplified Th17 responses could have a stronger influence on the development of imiquimod-induced skin inflammation than a decrease in TNF-α and IL-6 in IRF5 KO mice." (PMID 32456211, 2020). "Firstly, disruption in TNF stimulated linear ubiquitination can result in severe dermatitis." (PMID 32671059, 2020). "Therefore, it is difficult to conclude which are more important for imiquimod-induced skin inflammation, Th17 cytokines or inflammatory cytokines including TNF-α and IL-6." (PMID 32456211, 2020). "The epidermal ablation of cFLIP in TNF-deficient animals resulted in a significant amelioration of clinically evident skin inflammation compared to cFLIP animals not lacking TNF 5 days after the first tamoxifen application." (PMID 33238518, 2020). "We studied the synergistic effects of RR on keratinocytes and demonstrated that RR potently suppressed skin inflammation by inhibiting expression of pro-inflammatory cytokines, such as IL-6 and IL-1β in TNF-α/INF-γ-induced human keratinocytes and 3D human skin tissue model." (PMID 30901835, 2019). "But TNFα expression related to skin inflammation was decreased by the substance." (PMID 30622619, 2018). "Collectively, our study indicates that bathing with HMW ameliorates DNCB-induced skin inflammation by inhibiting the allergic response (such as serum IgE level and scratching behavior), inflammatory response (such as inflammatory cytokines; IL-1β, TNF-α, and IL-13) in female skh-1 hairless mice." (PMID 29029618, 2017). "The HIGH and the LOW phenotypes from the conventional mice were clearly transferred to germ-free mice, as there was a higher expression of dermatitis score, ear thickness, IL-1β, TNFα, IL-4, and IL-6 in the HIGH mice compared to the LOW mice, and for most of these also higher than the CONV mice." (PMID 28290517, 2017). "The ant-inflammatory and immunodulatory actions of Exc-B have been observed in TPA-induced inflammation and dermatitis in murine skin, as well as in LPS-induced mouse bone marrow-derived dendritic cells, with the reduction of IL-6 and TNF-α protein expressions." (PMID 28067799, 2017). "In particular, tumor necrosis factor-α (TNF-α), which plays an important role in the initiation and persistence of inflammation in a variety of skin disorders, can potently stimulate LCs, inducing their activation, in situ motility and pathogen sensing, and antigen presentation." (PMID 29238347, 2017).
dermatitis (continued). "Double deficient Sharpincpdm/cpdm;Tnfrsf1a−/− mice did not develop skin inflammation, demonstrating that TNF-induced TNFR1 signaling is essential for the pathogenesis of inflammatory skin lesions in Sharpincpdm/cpdm mice." (PMID 25443631, 2014). "It have been reported that other herbal medicine containing astragalus have anti-inflammatory activity through decreasing inflammation related cytokine, Tumor Necrosis Factor (TNF) alpha and Interferon gamma in a rat autoimmune myocarditis model, mice dermatitis model and diabetic mice." (PMID 22230247, 2012). "It remains unseen whether production of TNFα in antigen-presenting cells and keratinocytes is influenced by miR-16 and whether this regulatory pathway is affected during skin inflammation." (PMID 20594301, 2010). "Numerous studies have demonstrated that probiotics can alleviate skin inflammation and enhance skin barrier function in AD patients by promoting the activity of regulatory T cells (Tregs) and suppressing the production of pro-inflammatory cytokines, including IL-6 and TNF-α." (PMID 40630180, 2025). "However, the effects of RA on Dermatophagoides farinae extract (DfE)-induced AD-like skin inflammation, as well as its ability to regulate oxidative stress through the Nrf2/HO-1 pathway in TNF-α/IFN-γ-treated keratinocytes, remain unclear." (PMID 39684446, 2024). "Dermatitis is an inflammatory cutaneous condition where the disease progression is thought to involve a complex interaction of various inflammatory cytokines, such as interleukin-6 (IL-6) and tumor necrosis factor-alpha (TNF-α), along with the accumulation of oxidative stress." (PMID 39519149, 2024). "Similarly, IKK signalling in keratinocytes blocks TNF-induced apoptosis, preventing dermatitis." (PMID 39145956, 2024). "Furthermore, TNF-α plays a critical role in skin inflammation in contact dermatitis and psoriasis." (PMID 30718736, 2019). "To elucidate whether the aggravation of dermatitis and pruritus induced by FA exposure is related to the changes in skin Th1 cytokines, we examined whether exposure to 1.2 ppm of FA increased the expression of skin TNF-α and IL-1β in AD and naive rats." (PMID 28005965, 2016). "However, the dermatitis in CASP8-deficient mice is not affected by absence of TNF or IL1-receptor signaling, in contrast to Sharpincpdm mice." (PMID 24465642, 2014). "Pathway analysis also revealed robust activation of TNF and IFN-γ pathways in CLE keratinocytes, indicating the elaboration of these key cytokines at the interface dermatitis of CLE." (PMID 40409678, 2025). "Topical application of SPE decreased the development of AD-like skin inflammation in DFE-treated NC/Nga mice and IFN-γ/TNF-α-treated skin cells." (PMID 40362429, 2025). "PA significantly reduced reactive oxygen species (ROS) production, and both PA and LA suppressed pro-inflammatory cytokine expression in TNF-α/IFN-γ-stimulated HaCaT cells, consistent with their known anti-inflammatory roles in skin disorders." (PMID 40805794, 2025). "Its targets include chemokines and cytokines, such as tumor necrosis factor (TNF), IL 1-alpha (IL-1α), IL-1 β, and C-X-C motif chemokine ligand (CXCL8), crucial for skin inflammation." (PMID 39337376, 2024). "The increases in TCF4 in these mice further validate the capacity for skin inflammation to regulate TCF4 expression, with KC data suggesting that TNF-α, IL-17A, and IL-17C likely contribute to regulating (decreasing) TCF4." (PMID 38470486, 2024). "The DII is correlated with inflammatory biomarkers such as C-reactive protein (CRP), interleukin (IL)-6, and tumor necrosis factor (TNF)-α in various ethnic groups, and those inflammatory biomarkers contribute to the development and progression of dermatitis." (PMID 39464683, 2024). "We investigated RA activity in a DfE-induced AD-like skin inflammation mouse model and IFN-γ/TNF-α-stimulated keratinocytes." (PMID 39684446, 2024).
dermatitis (continued). "IFN-γ/TNF-α increased the levels of five chemokines (RANTES, TARC, eotaxin, MCP-1, and MIP-1α) related to skin inflammation in HaCaT cells." (PMID 39684446, 2024). "The HFD decreased mRNA expression of IL-17A, IL-17F, IL-22, TNF-α, IL-1β, CXCL1, CXCL2, and keratin 16, and increased mRNA expression of TGF-β1 and CDKN1A in imiquimod-induced dermatitis." (PMID 37762500, 2023). "Oral propionate reduced inflammatory infiltrates and epidermal Ki67+ cells and reduced mRNA levels of IL-17A, IL-17F, IL-17C, IL-22, IL-1β, IL-6, TNF-α, CXCL1, CCL20 and increased those of TGF-β1and IL-10 in imiquimod-indued dermatitis." (PMID 37762500, 2023). "Oral propionate decreased mRNA expression of IL-17A, IL-17C, IL-17F, IL-22, IL-6, IL-1β, TNF-α, CXCL1, and CCL20 in imiquimod-induced dermatitis in comparison between NDIS versus NDIP." (PMID 37762500, 2023). "During skin inflammation, proteolytic enzymes trypsin and tryptase signal pro-inflammatory factors through PAR-2, leading to the production of chemokines and cytokines like TNFα, IL-4, and TSLP." (PMID 37511138, 2023). "Another study showed that T-MSC injection in an AD mouse model reduced skin inflammation, mast cell infiltration, IgE production, and inflammatory cytokines such as IL6 and TNF-α." (PMID 38201284, 2023). "Oral propionate and the HFD reduced mRNA expression of IL-17A, IL-17C, IL-17F, IL-22, IL-1β, IL-6, TNF-α, CXCL1, CXCL2, and CCL20 in imiquimod-induced dermatitis." (PMID 37762500, 2023). "In our study, the levels of IL-4, TNF-α, INF-γ, and IgE in serum were reduced; meanwhile, the inflammation of back skin, the skin inflammation score, and the ear swelling of mice were alleviated after taking the TXS." (PMID 35646146, 2022). "For UV-induced skin disorders, paeonol ameliorates SUV-induced skin inflammation by inhibiting the increase of TOPK, the phosphorylation of p38, JNKs and H2AX, and the secretion of IL-6 and TNF-α in Babl/c mouse." (PMID 35095512, 2021). "Proinflammatory cytokines and chemokines secreted by keratinocytes, such as TNF-α, IFN-γ, IL-1β, IL-6, IL-8, TARC (CCL17), MDC (CCL22), and RANTES, play a very important role in dermatitis." (PMID 34361003, 2021). "Specifically, we observed attenuation of skin inflammation and a significant reduction in expression of mast cell mediators such as CCL2, IL-6, TNFα and MMP9 in the presence of osthole." (PMID 32391014, 2020). "Malt1-KO mice that develop skin inflammation were found to have increased serum levels of the pro-inflammatory cytokines IL-2, IL-4, IL-6, IL-17, IFN-γ, and TNF." (PMID 31632405, 2019). "Previous studies have demonstrated that components of the TNF-signaling pathway, NLRP3 inflammasome and IL-1R signaling are required to provoke skin inflammation in Sharpincpdm mice." (PMID 27892465, 2016). "Acutely, interleukin-1 (IL-1) and tumor necrosis factor-alpha (TNF-α) drive erythema and dermatitis, upregulating metalloproteases which degrade the dermis, particularly the basal layer." (PMID 26783706, 2015). "Likewise increased keratinocyte apoptosis may contribute to inflammation, and is also tied to NFKB, as supported by the increased sensitivity of SHARPIN-deficient cells to TNF-induced necroptosis and the lack of dermatitis in TNF-deficient Sharpincpdm mice." (PMID 24465642, 2014). "Several previous studies have suggested that EPA and DHA diet alleviate ear oedema and inhibit the production of pro-inflammatory factors (IκB, MAPKs, TNF-α, IL-6 and COX-2) in experimental skin inflammation models." (PMID 22873180, 2012). "Collectively, these findings indicate that Ohwia caudata leaf hydroethanolic extract exerts anti-inflammatory effects through a dual mechanism: downregulation of IL-6 and TNF-α and restoration of TGF-β expression, thereby alleviating TPA-induced skin inflammation." (PMID 41302132, 2025).
dermatitis (continued). "Tamoxifen-induced expression of CARD14E138A in Card14LSL-E138A mice rapidly induces TNF-dependent psoriasiform skin inflammation, which is independent of adaptive immune cells and due to signalling in keratinocytes, which express high levels of CARD14." (PMID 39145956, 2024). "Notably, in cultured primary human keratinocytes (KC), IL-17A synergizes with IL-22 and tumor necrosis factor (TNF)-α to induce the expression of IL-36, a cytokine with critical involvement in skin inflammation." (PMID 39600699, 2024). "TNF-α and IFN-γ (TI) are commonly used immune factors in dermatitis models, which can mimic the occurrence and progression of dermatitis by activating the immune response and disrupting the skin barrier function, thereby providing a reliable experimental model for related research." (PMID 39861084, 2024). "Furthermore, we examined the level of inflammatory cytokines, including IL-6 and TNF-α, in the DNCB-induced dermatitis animal model." (PMID 39519149, 2024). "The protective effects of PF and PW on UVB-induced skin inflammation and skin barrier damage in human immortalised epidermal keratinocytes (HaCaT) cells (including cell viability, ROS, HO-1, NQO1, IL-1β, IL-8, TNF-α, KLK-7, FLG, AQP3 and Caspase 14 levels) are investigated." (PMID 36771204, 2023). "All mice with oxazolone-induced dermatitis had a dramatic increase in IL-1β, IL-4, IL-6, IL-10, TNF-α, IFN-γ, IL-16, IL-17C, IL-17E, IL-17F, IL-21, IL-22, and MIP-3a, whereas the concentrations of IL-12p70, IL-2, IL-17A, and IL-23 were lower in dermatitis mice." (PMID 37889696, 2023). "HFD reduced mRNA levels of IL-17A, IL-17F, IL-22, IL-1β, tumor necrosis factor (TNF)-α, CXCL1, CXCL2, and keratin 16 and increased those of transforming growth factor (TGF)-β1 and cyclin-dependent kinase inhibitor 1A in imiquimod-induced dermatitis." (PMID 37762500, 2023). "Topical application of CLA significantly inhibited pro-inflammatory cytokines, including interleukin (IL)-6, IL-1β, tumor necrosis factor (TNF)-α, and the expression of the pro-inflammatory enzymes inducible nitric oxide synthase (iNOS) and cyclooxygenase-2 (COX-2) in mouse dermatitis." (PMID 38139380, 2023). "Anti-TNFα agents, particularly ADA, followed by UST and VED, play a role in the onset of dermatological pathologies, including urticaria, erythema, and dermatitis; moreover, our data showed a higher incidence of malignancies with VED when adjusted on 10 years of treatment." (PMID 36552036, 2022). "Beyond the direct phototoxic effects on the target tissues, various cytokines (such as interleukin-1β and tumor necrosis factor-α) and matrix metalloproteinase-1 are also secreted by fibroblasts during PDT, resulting in immunomodulatory effects in skin disorders." (PMID 36425335, 2022). "We identified a critical role of proinflammatory cytokines such as TNF-α, IFN-γ, IL-2 and IL-17A in skin inflammation in this model and revealed that these cytokines may be regulated by SHP2 in vitro." (PMID 34456714, 2021). "Previous studies have suggested CRH might activate mast cells to release pro-inflammatory mediators, such as IL-8, tumor necrosis factor (TNF), and vascular endothelial growth factor (VEGF), which are known to contribute to skin inflammation in AD." (PMID 32714398, 2020). "The Sharpincpdm/cpdmRipk3–/– or Sharpincpdm/cpdmMlkl–/– mice, which were competent for TNF-induced apoptosis but not necroptosis, still developed dermatitis." (PMID 31457011, 2019). "Our data indicate that, while TNF-induced cell death triggers the chronic inflammation and proliferative dermatitis, absence of SHARPIN-dependent integrin inhibition exacerbates the epidermal hyperproliferation in Sharpincpdm/cpdm mice." (PMID 29040328, 2017). "Thus, we believe that the elevated levels of inflammatory cytokines, including TNF-α and IL-1, in the blood of DNCB-induced dermatitis mice regulate their recruitment to inflamed sites and subsequent expansion, as well as promote myeloid differentiation." (PMID 26441031, 2015).
dermatitis (continued). "Aryl hydrocarbon receptor (AhR) activation suppresses autophagy and promotes skin inflammation through the NF-Kappa B (NF-κB)/p38 mitogen-activated protein kinase (MAPK) signaling pathway, leading to inflammatory cytokine secretion (IL-1β, IL-6, and TNF-α) in keratinocytes." (PMID 40332377, 2025). "WEIF components also blocked the JAK/STAT signaling pathway in TNF-α- and IFN-γ-stimulated keratinocytes with high binding affinities for JAK proteins, which might contribute to the inhibitory effect of WEIF on DfE-induced AD-like skin inflammation." (PMID 40806199, 2025). "Stimulation with TNF-α/IFN-γ induces the production of pruritic cytokines and chemotactic chemokines in keratinocytes such as TSLP, IL-31, CCL17/TARC, and CCL22/MDC, further expanding skin inflammation with the recruitment of major T cell lineage, Th2 cells, resulting in epidermal damage." (PMID 37958804, 2023). "Since deficiency of caspase-8 or FADD alone in epidermal keratinocytes triggers a RIPK3-dependent skin inflammation, we could not directly investigate the role of FADD or caspase-8 in the TNF-induced death of Sharpin-deficient keratinocytes in vivo." (PMID 25443631, 2014). "Furthermore, our preliminary results show that the digested EBN could ameliorate TNF-α induced dermatitis in keratinocytes (data not shown), which supports a greater potential of EBN in developing into anti-inflammatory and moisturizing skincare products." (PMID 34354585, 2021). "As keratinocyte apoptosis and skin inflammation in Sharpincpdm/cpdm mice were suppressed by epidermal-specific deletion of FADD or TRADD, we sought to investigate how the lack of FADD, TRADD, and RIPK3 proteins impact on TNF-induced cell viability in Sharpin-deficient cells." (PMID 25443631, 2014). "Mechanistically, an increase in TNF-induced keratinocyte apoptosis in the absence of LUBAC-mediated NF-kB signaling drives the systemic inflammation and hyperproliferative dermatitis in Sharpincpdm/cpdm mice." (PMID 29040328, 2017). "A negative TCF4/IL-17C/ TNF-a/ IL-17A feedback loop decreases TCF4 in an IL-17RA/RE-dependent manner and is further amplified by IL-17C/TCF4 regulation of ZC3H12A and IL-17C regulation of NFKBIZ, resulting in self-sustaining skin inflammation." (PMID 38470486, 2024).